IGKV3-7 (immunoglobulin kappa variable 3-7 (non-functional))
Description:
Probable non-functional open reading frame (ORF) of V region of the variable domain of immunoglobulin light chains. Non-functional ORF generally cannot participate in the synthesis of a productive immunoglobulin chain due to altered V- (D)-J or switch recombination and/or splicing site (at mRNA level) and/or conserved amino acid change (protein level). Immunoglobulins, also known as antibodies, are membrane-bound or secreted glycoproteins produced by B lymphocytes. In the recognition phase of humoral immunity, the membrane-bound immunoglobulins serve as receptors which, upon binding of a specific antigen, trigger the clonal expansion and differentiation of B lymphocytes into immunoglobulins-secreting plasma cells. Secreted immunoglobulins mediate the effector phase of humoral immunity, which results in the elimination of bound antigens. The antigen binding site is formed by the variable domain of one heavy chain, together with that of its associated light chain. Thus, each immunoglobulin has two antigen binding sites with remarkable affinity for a particular antigen. The variable domains are assembled by a process called V-(D)-J rearrangement and can then be subjected to somatic hypermutations which, after exposure to antigen and selection, allow affinity maturation for a particular antigen.
Synonyms: IGKV37; L10; L10a; Vh
Gene: Immunoglobulin variable (V) gene on chromosome 2 (88,978,468 to 88,979,081, reverse strand). Ensembl gene ENSG00000243063.
Subcellular location: Secreted; Cell membrane
Subcellular location (Human Protein Atlas): Cytosol; Plasma membrane; Predicted to be secreted
Gene Ontology:
Biological process: immune response
Cellular component: extracellular region; immunoglobulin complex; plasma membrane
Homologues: Orthologues: mouse Igkv18-36 (64% identical), rat Igkvl13 (62% identical). Paralogues in human: IGKV3OR2-268 (96% identical), IGKV3D-7 (91% identical), IGKV3-11 (89% identical), IGKV3-15 (89% identical), IGKV3-20 (87% identical), IGKV3D-11 (87% identical), IGKV3D-15 (87% identical), IGKV3D-20 (84% identical), IGKV1-39 (71% identical), IGKV1D-39 (71% identical), IGKV1D-8 (70% identical), IGKV1-6 (69% identical), and 81 more.
Diseases named in the same sentence as IGKV3-7 in open-access papers:
IGKV3-7 is named in the same sentence as 2 diseases in open-access papers, as found by Europe PMC text mining. Sharing a sentence is not in itself a finding about the gene and the disease. The quoted sentences say what the papers report.
COVID-19 (1 paper, 2025). A disease caused by infection with severe acute respiratory syndrome coronavirus 2. "In particular, two independent studies revealed significant upregulation of IGKV3-7 in asymptomatic COVID-19 individuals and IGLV9-49 in COVID-19 patients respectively, which implies that these two proteins may be involved in acute lung inflammation." (PMID 39358504, 2025).
preeclampsia (1 paper, 2025). Preeclampsia is a hypertensive disorder of pregnancy that is characterized by new-onset hypertension with proteinuria presenting after 20 weeks of gestation, and depending on mild or severe forms may initially present with severe headache, visual disturbances, and hyperreflexia. "Additionally, SAA4, ANG, CFHR5, IGKV3-7, and PAPPA have been suggested to play a role in the context of preeclampsia." (PMID 40974471, 2025).